IL1B (interleukin 1 beta)
Diseases named in the same sentence as IL1B in open-access papers (continued):
Sharing a sentence is not in itself a finding about the gene and the disease.
glioma (196 papers, 1999 to 2025). A benign or malignant brain and spinal cord tumor that arises from glial cells (astrocytes, oligodendrocytes, ependymal cells). "Closely associated with TNF-α signaling is interleukin-1 beta (IL-1β), another critical pro-inflammatory cytokine involved in shaping the glioma microenvironment." (PMID 40565357, 2025). "Interruption of this cellular circuit using glutamate receptor, IL-1β or Ccl5 inhibitors abrogates injury-induced glioma progression, thus establishing a causative relationship between injury and tumorigenesis." (PMID 38308315, 2024). "Particularly, high-grade glioma-associated microglia were observed to secrete IL-1β via the NLRP1 inflammasome, promoting tumor progression." (PMID 37749707, 2023). "We found that higher expression of the IL1B signature is associated with lower survival rate in multiple cancer types, especially in Low Grade Glioma (LGG) and in Kidney renal cell carcinoma (KIRC)." (PMID 37149682, 2023). "Cx3Cr1-deficient microglia/macrophages upregulate IL1β and promote enhanced glioma growth with an enhanced stem cell phenotype." (PMID 35884391, 2022). "IL-1β secretion by tumor-associated macrophages in gliomas presents an essential role in tumor maintenance." (PMID 35784465, 2022). "So we also substantiated a crucially positive correlation of the risk score with IL-1α, IL-1β, IL-6, IL-8, and IL-18 expression levels in patients with glioma." (PMID 34114970, 2021). "On the contrary, TCGA analysis on glioma patient samples shows that high expression of “IL1B-signature” is correlated with high expression of CD133 (a marker of glioma aggressiveness) and associated with poor prognosis." (PMID 32635472, 2020). "Taken together, these results indicate that increased expression of IL-1β and IL-18 is associated with poor prognostic outcomes for glioma patients." (PMID 31139563, 2019). "We first performed clinical data analysis to determine the association of IL-1β and IL-18 expression with clinical and molecular characteristics in gliomas." (PMID 31139563, 2019). "We first found that IL-1β promotes glioma spheroid formation and is associated with elevated CEBPD expression." (PMID 31300060, 2019). "Gliomas contain high levels of inflammatory cytokines, namely IL-1β, IL-6, and IL-8, which are associated with increase invasion levels." (PMID 25596741, 2015). "Conversely, in vitro, IL-1β has been implicated in inducing glioma invasion, as well as promoting tumor growth via autocrine induction of TNF signaling." (PMID 23596394, 2013). "Besides, IL-1β from HMC3 cells promoted glioma progression and caused activation of nuclear factor-κB (NF-κB) and upregulation of HPSE in vivo." (PMID 38863009, 2024). "IL-1β secreted by tumor-associated macrophages/microglia has been reported to upregulate other proinflammatory cytokines, promote angiogenesis, and influence almost every step of the glioma progression." (PMID 36389690, 2022). "IL-1β released from the macrophage M2 phenotype caused glioma cell migration." (PMID 34439380, 2021). "In murine gliomas at the asymptotic phase, MDMs upregulated Il-1b that encodes an inflammatory cytokine, along with genes encoding inflammatory cytokine inhibitors Il1rn and Il18, and there was a subset with a high expression of the Cd274 mRNA encoding an immune-checkpoint inhibitor (PD-L1)." (PMID 33809675, 2021). "Glioma-associated microglia and macrophages release several cytokines and growth factors (interleukin (IL) IL-6, IL-1β, transforming growth factor-β (TGF-β)), epidermal growth factor (EGF), and stress-inducible protein 1 (STI1) that facilitate the tumor proliferation and migration." (PMID 28346397, 2017). "To further understand the implications of using tumor-based exosomes to induce desired cell types in vitro, we explored the possibility that NSCs treated with exosomes from unchallenged and IL-1β-challenged U87 cells might induce expression of proteins associated with glioma such as CD133." (PMID 32649728, 2020).
glioma (continued). "While IL-1β can activate the NF-κB transcription factor within 20 min in a rat glioma cell model, prolonged exposure (48–72 h) to IL-1β in human astrocytes results in cellular impairment and apoptosis, involving the activation of cleaved caspase-3." (PMID 41227382, 2025). "In LN-229 glioma cells, IL-1β and TGF-β made the cells form neurosphere and increased the presence of Bmi-1 and nestin genes related to tumor stemness." (PMID 40727443, 2025). "Neutrophils are recruited to glioma inflammatory regions by chemokines such as CXCL1, CXCL2, CXCL3, CXCL5, CXCL6, IL-8 (CXCL8), and IL-1β, which are secreted by glioma cells." (PMID 41272822, 2025). "Inflammatory and glioma cells express and can release SP that regulates neurogenic inflammation mediated by the release of IL-1β, IL-6, IL-8, TNF-α, GM-CSF, and LIF." (PMID 39941886, 2025). "Proinflammatory IL-1β stimulates glioma cells to produce TGF-β, which mediates subsequent upregulation of VEGF, leading to tumor proliferation via increased angiogenesis." (PMID 38247852, 2024). "Simultaneously, we demonstrated that inhibiting p-STAT3 through EZH2 enhances NLRP3 inflammasome activity, promoting glioma pyroptosis and the expression of inflammatory factors IL-1β and IL-18." (PMID 39069522, 2024). "In fact, IL‐1β promotes glycolysis in gliomas through the IL‐1β‐protein kinase‐δ (PKCδ)‐glycolysis enzyme‐3‐phosphate dehydrogenase (GPD2) axis, which reprograms cellular metabolism and can promote tumour proliferation and tumour metastasis." (PMID 38652105, 2024). "Results demonstrated that, when cocultured with DHX9‐overexpressed glioma cells, macrophages exhibited decreased expression of M1 markers (IL‐1b, IL‐12b, and TNF‐α) and increased expression of M2 markers (IL‐10, CD163, and ARG1)." (PMID 36377508, 2023). "Our data demonstrates that glioma patients present an important cytokine-related worse outcome, especially regarding IL-1β and IL-10." (PMID 37292196, 2023). "Mechanistically, LINC01116 directly binds to and recruits DDX5 to the IL-1β gene promoter in glioma cells to increase the expression of IL-1β which in turn promotes glioma progression and recruits neutrophil to glioma." (PMID 37596619, 2023). "In the first 24 h, glioma-neutrophil cultures produced high amounts of IL-8 and TNFα, slightly increased amounts of IL-12p70, and low to zero levels of IL-1β, IL-6, and IL-10." (PMID 37292196, 2023). "Berberine directly inhibits caspase-1 activation via the ERK1/2 signaling pathway in glioma cells, leading to inhibition of the expression of pro-inflammatory cytokines such as IL-1β and IL-18." (PMID 37723542, 2023). "Another report has exhibited that the NLRP3 inflammasome induces proliferation and invasion of glioma cells via regulation of IL-1β and NF-κB p65 signaling." (PMID 37723542, 2023). "The lactate-IL-1b-Clock/Bmal1 loop positively affected a number of pathways including cell cycle, DNA damage and cytoskeletal organization in glioma." (PMID 37476290, 2023). "Hyperactivation of NLRP3-AKT axis, and its IL-1β/NF-kB p65 downstream pathway, has been detected in glioma cells and held responsible for cancer proliferation and migration." (PMID 37891577, 2023). "TNF-α and IL-1β are pro-inflammatory cytokines that are found in supratentorial high-grade gliomas and are involved in neuroinflammation, gliomagenesis, and development of radio-resistance." (PMID 37752585, 2023). "IL-1β is known to fuel microglial polarisation into a trophic, immunosuppressive phenotype ideal for glioma growth." (PMID 37225786, 2023). "Other studies have also demonstrated that TAM-derived factors such as VEGF, EGF, bFGF, IL-1β and IL-6 are able to facilitate glioma vascularization." (PMID 37705736, 2023). "To identify the source of IL-1β, we used FACS to isolate tumor-associated MG, BMDMs, and glioma cells for Il1b real-time quantitative PCR." (PMID 37733448, 2023).
glioma (continued). "Cytokines IL-1β and TNF-α are generally recognized as inhibitors of glioma growth and associated with better prognosis." (PMID 36675073, 2023). "According to our observations, IL-1β expression was restricted to peritumoral astrocytes, while in gliomas, both the host cells and the tumor cells were shown to take part in inflammasome signaling." (PMID 37749707, 2023). "A study using the U251MG human glioma cell line showed that IL-1β stimulates the production of IL-6 and IL-8, which in turn promotes cell invasion." (PMID 36675073, 2023). "TGF-β1 secreted by glioma cells activates microglia in tumors and secretes IL-1β through lipoprotein E (ApoE)-mediated NLRP1 inflammasome." (PMID 37700840, 2023). "Glioma-associated macrophages have been revealed to express several significant modulators that induce glioma growth and invasion, including IL-1β, TGF-β, IL-6, epidermal growth factor (EGF), and STI1, by modulating the perivascular GICs and glioma cells." (PMID 37012233, 2023). "Our findings provide evidence of a feed-forward lactate-IL-1b-Clock/Bmal1 loop that drives tumor progression by driving aberrant metabolism and inflammation in glioma." (PMID 37476290, 2023). "On the one hand, glioma is a highly pro-inflammatory tumor since the abundant secretion of pro-inflammatory factors, such as IL-1β, IL-6, and high mobility group box protein (HMGB1) through the autocrine or paracrine mechanism accelerates tumor growth." (PMID 35990696, 2022). "IL-1β-induced ERK activation can also have mitogenic effects on human glioma U373MG cells and significantly increase GBM cell proliferation." (PMID 35626018, 2022). "LINC01116, a long noncoding RNA expressed in glioma tissue, can promote IL-1β expression by recruiting the transcriptional regulator DDX5 to the IL-1β promoter." (PMID 35860278, 2022). "GBMs have been shown to produce large amounts of IL-1β, which plays a key role in glioma aggressiveness and survival." (PMID 35626018, 2022). "Our results, thus, indicate the involvement of editing-regulated inflammatory response in glioma progression, consistent with the observation that IL1β blockade inhibited granulocytic monocytic myeloid-derived suppressor cells in female GBM patients." (PMID 35406793, 2022). "LINC01116 recruits DDX5 to the IL-1β promoter and activates IL-1β expression to promote neutrophil recruitment and glioma proliferation." (PMID 35992805, 2022). "Blocking IL-1β generated by macrophages or Inhibition of PKCδ or GPD2 pT10 in glioma cells attenuated the glycolytic rate and proliferation of glioma cells." (PMID 35600367, 2022). "The expression of proinflammatory cytokines such as TNF-α, IL-6 and IL-1β induced by LPS treatment was dose-dependently attenuated in IOE-treated C6 glioma cells." (PMID 36670940, 2022). "This renounces the antitumor activity and contributes to glioma invasion, releasing multiple cytokines, i.e., IL-1β, IL-6, IL-8, IL-10, and TNF-α." (PMID 35454935, 2022). "A study revealed that the significance of IL-1β lies in the IL-1β/CCL2/IL-6 interaction between microglia as well as glioma cells." (PMID 35419058, 2022). "The volcano plot revealed that glial cells in C5 derived from TDL upregulated expression of myelin-related genes (TYMP, CD9, MAG, and PMP22) and immune-related and inflammatory response-associated genes (IL1B and CXCL8) comparing to those from glioma." (PMID 36085357, 2022). "Another example is that IL-1β stimulates GDNF expression in C6 glioma cells through the inhibitor kappa B (IκB), p38 MAP kinase, p44/p42 MAP kinase and JAK-STAT3 pathways." (PMID 36055989, 2022). "Blocking NF-κB attenuates IL-1β and NLRP3 overexpression and increases cell growth and invasion, and NLRP3 promotes glioma growth and invasion through IL-1β/ NF-κB P65 signaling." (PMID 36401196, 2022). "Recent results show that TAMs secrete IL-1β, which promotes the rate of glycolysis in glioma cells through glycerol-3-phosphate dehydrogenase (GPD) enzyme." (PMID 34503065, 2021).
glioma (continued). "Hindering IL-1β signaling in TAMs attenuated the glycolysis rate and cell proliferation of glioma cells in vitro." (PMID 34503065, 2021). "Human GBM cell lines and cultured primary glioma cells can secrete a large amount of IL-1β, IL-6 and IL-8, and promote tumor growth in an autocrine or paracrine way." (PMID 34830775, 2021). "Glioma-derived pro-inflammatory factors, IL-1β, IL-6, TNF-α, and COX-2, were found to accelerate p38 MAPK phosphorylation." (PMID 34439380, 2021). "Glioma progression accompanying neutrophil recruitment is also mediated by the long non-coding RNA LINC01116-triggered IL-1β upregulation." (PMID 34671362, 2021). "In patient-derived glioma tissue, staining for IL-1β and macrophages correlates with PKCδ and GAP3DH, and this is associated with higher glioma grade and lower overall survival." (PMID 34073734, 2021). "TLR-4 activation in human glioma U251 cells stimulated the production of cytokines (IL-1β, IL-6, IL-8, and TNFα) and increased the expression of stem cell markers such as CD133 and CD34." (PMID 34439380, 2021). "In contrast, NLRP3 overexpression promotes the growth and invasion of gliomas through IL-1β/NF-κB p65 signaling." (PMID 34239588, 2021). "Significant increase in the LDH and IL-1β level in the supernatants were detected when glioma cells treated with TMZ using ELISA kits." (PMID 34830775, 2021). "On the other hand, the increase of NLRP3, ASC, caspase-1, and IL-1β proteins in human glioma tissues is significantly correlated with higher World Health Organization grades." (PMID 33613533, 2020). "Western blot and ELISA also demonstrated that the protein level of IL-1β was significantly decreased in LINC01116-lowexpressed glioma cells." (PMID 32358484, 2020). "In summary, our current work showed that LINC01116 promoted tumor proliferation and neutrophil recruitment by regulating IL-1β in glioma." (PMID 32358484, 2020). "On the basis of these results, LINC01116 contributes to many biological functions during the progression of glioma by regulating IL-1β." (PMID 32358484, 2020). "To further investigate the role of IL-1β in glioma, we incubated Ln229 or U87 cells with IL-1β (10 ng/ml) for 24 h and showed significant increases in glioma cell growth/viability." (PMID 32358484, 2020). "LINC01116 induced IL-1β transcription via DDX5 in glioma cells to promote tumor proliferation and recruit TANs, which participated in the pro-tumor process via producing a host of cytokines." (PMID 32358484, 2020). "We further examined the effects of these exosomes on rat fetal neural stem cell (rNSC) differentiation using the secreted exosomes from U87 glioma cells or exosomes from U87 cells that were stimulated with interleukin 1β (IL-1β)." (PMID 32649728, 2020). "RNA-seq analysis demonstrated that LINC01116 knockdown affected the expression of IL-1β, which promoted glioma proliferation and neutrophil recruitment." (PMID 32358484, 2020). "In human glioma, IL-1β-related inflammation promotes cancer malignancy and is markedly amplified through the crosstalk of cancer cells with surrounding immune cells." (PMID 32069807, 2020). "In the meningioma and glioma group, IL-1β level was statistically higher than the control group (p=0.03, p=0.001)." (PMID 31653130, 2019). "The contribution of IL-1β to the progression of human glioma by influencing proliferation, migration, and invasion as well as the development of the tumor microenvironment has been previously well-documented." (PMID 31475119, 2019). "Due to the histopathological heterogeneity of gliomas, mRNA levels of IL-1β and IL-18 in gliomas were analyzed according to the WHO grade system and histology." (PMID 31139563, 2019). "Other findings, were increased levels of IL-1β in the sera of glioma and meningioma patients that strongly correlated with tumor grade and clinical aggressiveness in glioblastoma." (PMID 31653130, 2019).
glioma (continued). "TNF-α and IL-1β expressions were significantly higher in the meningioma and glioma group in comparison to control group." (PMID 31653130, 2019). "Immunohistochemical analysis showed that the expression of IL-18 and IL-1β were significantly upregulated in glioma tissues compared to normal brain tissues." (PMID 31139563, 2019). "We first show that IL-1β is highly expressed in GBM, promotes glioma spheroid formation, and is associated with the elevated CEBPD expression." (PMID 31300060, 2019). "In the TCGA, CGGA, and REMBRANDT datasets, we demonstrated that the expression of IL-1β and IL-18 were significantly increased in grade IV gliomas, compared to those in WHO grade II and grade III gliomas." (PMID 31139563, 2019). "IL-1β is an isoform of the IL-1 cytokine superfamily secreted mainly by immune cells, including TAMs, while its receptor (IL-1R) has been found in glioma cells." (PMID 31231208, 2019). "Considering the fact that berberine significantly attenuates the production of IL-18 and IL-1β, which are normally highly expressed in gliomas, we questioned if berberine treatment would significantly decrease the viability of glioma cells." (PMID 31139563, 2019). "In this study, we have demonstrated that IL-1β-induced CEBPD promotes glioma stemness in U373MG, T98G, and PT#3-spheroid cells by elevating PDGFA expression." (PMID 31300060, 2019). "In this study, we demonstrate that berberine significantly inhibits inflammatory cytokine Caspase-1 activation via ERK1/2 signaling and subsequent production of IL-1β and IL-18 by glioma cells." (PMID 31139563, 2019). "Other studies also show that HIV-1 Tat can induce the secretion of TNFα and IL1β from U87 glioma cells." (PMID 30972014, 2019). "Following IL-1β treatment, the numbers of glioma spheroids significantly increased compared to those in untreated controls." (PMID 31300060, 2019). "On the other hand, previous report demonstrated that secreted IL-1β promotes chronic inflammation and induces glioma progression." (PMID 31133717, 2019). "IL-1β, IL-6, TGF-β, and EGF have been shown to promote glioma invasion from tumor-associated macrophage secretion." (PMID 31300060, 2019). "Microglial release of IL-1β can also be driven by the neuropeptide substance P (SP), which is expressed in both microglia and glioma cells, along with its receptor NK-1." (PMID 31231208, 2019). "Further, IL-1β and IL-18 expression was significantly increased in mesenchymal gliomas than other types of gliomas." (PMID 31139563, 2019). "Previous studies showed that increased secretion of IL-1β by glioma cells and in patients with IL-1β positive tumors had generally worsen the prognoses." (PMID 31653130, 2019). "Increased expression of IL-1β, IL-6, and IL-8 was also observed in glioma patient samples and was correlated with cancer invasiveness and survival of patients." (PMID 28881826, 2017). "As observed, COX-2 (Ptgs2), IL-1β, and CCL5 are among the 25 highest upregulated genes in glioma-associated microglia/macrophages." (PMID 29258556, 2017). "Glioma cells produce various inflammatory mediators, such as IL-1β, IL-6, IL-8, IL-10, MCP-1, and MIP." (PMID 28881826, 2017). "These experiments demonstrated that IL-1β induces HLA-G in glioma cells in a HIF-1α-dependent manner." (PMID 28781970, 2017). "Increased levels of HLA-G expression, promoter activity, and surface protein expression were detected in glioma cells cultured with the addition of IL-1β." (PMID 28781970, 2017). "The authors previously reported that IL-1β induces HIF-1α in glioma cells through an IL-1β-HIF-1α feedback loop." (PMID 28781970, 2017). "All these findings suggest that IL-1b-mediated neuroinflammatory cascades contribute to glioma progression." (PMID 28389653, 2017). "Recent evidence reported that cAMP/PKA enhances IL-1β induced-IL-6 synthesis through Jak2/Stat3 activation, identifying novel therapeutic targets for the treatment of glioma." (PMID 28157712, 2017).